MDM2 (MDM2 proto-oncogene)
Diseases named in the same sentence as MDM2 in open-access papers (continued):
Sharing a sentence is not in itself a finding about the gene and the disease.
Ewing sarcoma (24 papers, 2011 to 2026). A small round cell tumor that lacks morphologic, immunohistochemical, and electron microscopic evidence of neuroectodermal differentiation. "This is the first study evaluating both SATB2 and MDM2 expression in OS, BFOLs, and Ewing sarcoma of the jaw." (PMID 35049602, 2021). "Amplification of the CDK4 and MDM2 genes was found in Ewing's sarcoma." (PMID 37089080, 2023). "However, MDM2 amplification is a rare event in Ewing Sarcomas and is only observed in approximately 2% of ESFT cases." (PMID 21197471, 2011). "This study aims to determine the value of SATB2 and MDM2 immunohistochemistry (IHC) in differentiating OSJ from other jawbone mimickers, such as benign fibro-osseous lesions (BFOLs) of the jaw or Ewing sarcoma of the jaw." (PMID 35049602, 2021). "Twelve benign fibro-osseous lesions (seven ossifying fibromas and five fibrous dysplasias) of the jaw and a primary Ewing sarcoma of the jaw were also retrieved and evaluated for SATB2 and MDM2 immunohistochemistry (IHC)." (PMID 35049602, 2021). "MDM2-mediated ubiquitination of IGF-1R with PPP treatment leads to the activation of ERK pathway, resulting in the resistance of Ewing’s sarcoma to the treatment of the anti-IGF-1R antibody figitumuab." (PMID 24182354, 2013). "In this study, we evaluated the value of SATB2 and MDM2 IHC in differentiating OSJ from other common jawbone mimickers, such as benign fibro-osseous lesions (fibrous dysplasia and ossifying fibroma) of the jaw and primary Ewing sarcoma of the jaw." (PMID 35049602, 2021). "Our study found that 27% (3/11) of high-grade OSJs were positive for MDM2, while all BFOLs of the jaw and a Ewing sarcoma of the jaw were negative for MDM2." (PMID 35049602, 2021). "MDM2 was expressed in a weak to moderate intensity and scattered focal to limited diffuse staining pattern in 27% (3/11) of cases of OSJ and negative in all BFOLs and the Ewing sarcoma." (PMID 35049602, 2021).
soft tissue tumors (23 papers, 1997 to 2025). "A total of 79 patients with deep fatty soft tissue tumors were studied in our hospital, with immunohistochemical determination of MDM2 for the diagnosis of ALT." (PMID 39997549, 2025). "Overall, the overexpression of MDM2 in soft-tissue tumors contributes to the aggressive and malignant behavior of these tumors." (PMID 37297833, 2023). "Detection of MDM2 amplification in cell-free DNA of patients with different types of soft tissue tumors." (PMID 34986184, 2022). "Additionally, this tumor harbored high-level MDM2 amplification, an alteration more commonly observed in soft tissue tumors." (PMID 41230344, 2025). "Therefore, MDM2 has been identified as a potential therapeutic target for the treatment of soft-tissue tumors." (PMID 37297833, 2023). "In addition, a histopathological analysis was conducted by pathologists specialized in the analysis of soft-tissue tumors and included the immunohistochemistry for the assessment of the MDM2 status in all cases." (PMID 37046811, 2023). "However, further research is needed to fully understand the implications of MDM2 inhibition for the treatment of soft-tissue tumors and to determine the safety and efficacy of these therapies in clinical trials." (PMID 37297833, 2023). "Whilst MDM2 amplifications were found in cfDNA of 2/3 DDLPS patients, no amplification was present in the patient with WDLPS, or 11 patients with other soft tissue tumour types." (PMID 39797974, 2025). "For instance, ring chromosomes containing amplified copies of MDM2, often accompanied by CDK4, are also present in subtypes of soft tissue tumours." (PMID 39322633, 2024). "In the 64 soft tissue neoplasms in which pure DDL was in the differential diagnosis, MDM2 was amplified in only 21.9%." (PMID 25810689, 2015). "The patient with WDLPS and patients with other soft tissue tumors in differential diagnosis were negative for the MDM2 amplification in cell-free DNA." (PMID 34986184, 2022).
breast tumors (22 papers, 1996 to 2025). "Soon after Mdm2 was discovered, ERα was shown to associate with high levels of Mdm2 in breast tumors." (PMID 21223569, 2011). "MDM2 RNA expression levels were analysed in a subset of 57 breast tumours and overexpression was observed in 4/57 (7%) of the tumours." (PMID 8980401, 1996). "Overexpression of MDM2 has been observed in several cancer types including breast tumors." (PMID 33604794, 2021). "Having demonstrated that ERα regulates MDM4 and MDM2 mRNA expression, and additionally, that MDM4 and MDM2 mRNA expression is specifically elevated in ERα-positive primary human breast tumors, we postulated that ERα transcriptionally regulates MDM4 and MDM2 genes." (PMID 26909605, 2016). "Frequent overexpression of MDM2 in advanced breast tumors was observed." (PMID 24667108, 2014). "The expression levels of MDM4, MDM2, YAP1, and YPEL3 in human breast tumor samples were investigated compared to normal samples using TNM plot analysis." (PMID 39345743, 2024). "In addition, we demonstrate that tumors of luminal A and luminal B molecular subtypes have the highest expression of MDM2 and MDM4 mRNA, in agreement with a prior study that observed that MDM4 protein expression is similarly elevated in luminal A/B breast tumors." (PMID 26909605, 2016). "However, it is not known if MDM2 mRNA expression also correlates with ERα expression in primary breast tumors." (PMID 26909605, 2016).
intimal sarcoma (19 papers, 2011 to 2025). A malignant neoplasm arising from the large blood vessels. "Recently, Yamada et al22 reported that a myxoid histology in an intimal sarcoma is associated with an MDM2 amplification." (PMID 37395142, 2023). "Undifferentiated mesenchymal tumors arising from the inner lining (intima) of large arteries are classified as intimal sarcomas (ISA) with MDM2 amplification as their molecular hallmark." (PMID 34312479, 2021). "Similarly, intimal sarcomas exhibit a much higher frequency of MDM2/CDK4 amplification, which serves as a valuable diagnostic tool for pathologists." (PMID 38275873, 2024). "Additionally, the intimal sarcoma with a positive stain for MDM2 has been shown by some studies to be associated with a poor prognosis, with a median survival of three to twelve months." (PMID 38732333, 2024). "MDM2 amplifications emerged as the most frequent molecular alteration, consistent with findings in patients with intimal sarcoma and cardiac UPS." (PMID 40571919, 2025). "Overexpression of MDM2 in intimal sarcoma and C-MYC amplification in certain angiosarcomas, particularly secondary forms, are useful features for differential diagnosis." (PMID 41416324, 2025). "Takafumi noted that milademetan, an MDM2 inhibitor, showed effectiveness in patients with MDM2-amplified intimal sarcoma." (PMID 40078190, 2025). "By performing MDM2 reaction amid immunohistochemistry exams, seven cases were re-classified to actually be intimal sarcomas (positive MDM2 status)." (PMID 38732333, 2024). "One cohort retrospectively analysed 48 cases of primary cardiac sarcomas amid MDM2 testing, and fewer than half were intimal sarcomas (n = 15/48 patients; mean age of 47.2 years; range: 12–78 years)." (PMID 38732333, 2024). "Based on localization, morphology, and MDM2 amplification, intimal sarcoma was an additional suspected diagnosis." (PMID 38656400, 2024). "The copy number alterations further confirmed the MDM2 amplification but also revealed TERT amplification as well as CDKN2A/B deletion that are compatible with the diagnosis of intimal sarcoma." (PMID 38656400, 2024). "MDM2 positivity was correlated with tumor location, especially left atrium (p = 0.001), which is consistent with the common occurrence of intimal sarcoma at that location." (PMID 37395142, 2023). "Neuville et al5 suggested that the most frequent primary cardiac sarcoma is an intimal sarcoma based on the incidence of MDM2 amplifications." (PMID 37395142, 2023). "The accurate diagnosis of intimal sarcoma in high‐grade cardiac sarcoma using MDM2 IHC can have a significant impact on patient treatment and prognosis, and therefore, is important." (PMID 37395142, 2023). "A total of 15 patients were included in the analysis, and all MDM2 positive patients were classified as intimal sarcoma." (PMID 37395142, 2023). "Seven patients in our present cohort were given a revised diagnosis of intimal sarcoma in accordance with MDM2 immunopositivity." (PMID 37395142, 2023). "Although this was the initial diagnosis in one case, it was revised to an intimal sarcoma following our current MDM2 expression analysis." (PMID 37395142, 2023). "Many primary cardiac sarcomas with histological features of undifferentiated pleomorphic sarcoma are currently reported as intimal sarcomas, especially if there is MDM2 expression." (PMID 36983010, 2023). "DDLPS is one of the only tumor types (with intimal sarcomas) characterized by a consistent amplification of MDM2 and is therefore an ideal tumor type in which to evaluate the clinical activity of such compounds." (PMID 32806555, 2020). "The largest study of cardiac sarcomas analyzed tissue samples from 100 cases, and found intimal sarcomas to be the most frequent subtype of cardiac sarcoma, with amplification of MDM2 in all cases." (PMID 31480474, 2019).
intimal sarcoma (continued). "Seven cases (53.8%) were newly reclassified as an intimal sarcoma by IHC for MDM2." (PMID 37395142, 2023). "Moreover, MDM2 is also amplified in intimal sarcoma, low-grade central osteosarcoma, and parosteal osteosarcoma." (PMID 36983010, 2023). "Recently, MDM2 amplification reported to be a characteristic genetic event in the intimal sarcoma." (PMID 37395142, 2023). "The testing for MDM2 expression is mainly done to distinguish intimal sarcoma from UPS." (PMID 37395142, 2023). "Seven cases were reclassified as an intimal sarcoma in accordance with their MDM2 immunopositivity." (PMID 37395142, 2023). "Such case might be confused with tumors carrying MDM2 amplification, such as intimal sarcoma and a few pulmonary sarcomatoid carcinomas (PSC)." (PMID 36059611, 2022). "Another study of IS, which was the first to propose PDGFRA as a molecular hallmark for intimal sarcomas, found copy number gains of PDGFRA, EGFR, and MDM2 in 8 patients using FISH and aCGH with consistent activation of PDGFR and EGFR confirmed by western blotting." (PMID 31480474, 2019). "Additionally, it is known that not only MDM2 gene amplification but also CDK4 and PDGFR gene amplification can occur together in intimal sarcoma." (PMID 37395142, 2023). "MDM2 and PDGFR pathways may play a role in the pathogenesis of intimal sarcoma." (PMID 36983010, 2023). "To conclude, the myxoid histological report was correlated with MDM2 amplification and thus, intimal sarcoma sub-groups (myxoid and non-myxoid) might represent a new perspective of understanding different clinical behaviours since genetic and pathological backgrounds might be distinct." (PMID 38732333, 2024).